TLE2 (TLE family member 2, transcriptional corepressor)
Description:
Transcriptional corepressor that binds to a number of transcription factors. Inhibits the transcriptional activation mediated by CTNNB1 and TCF family members in Wnt signaling. The effects of full-length TLE family members may be modulated by association with dominant-negative AES (By similarity).
Synonyms: ESG2; GRG2; ESG; FLJ41188
Tractability: PROTAC: UniProt records ubiquitination sites on it; ubiquitination databases record sites on it.
Gene: Protein-coding gene on chromosome 19 (2,997,639 to 3,047,635, reverse strand). Ensembl gene ENSG00000065717.
Subcellular location: Nucleus
Subcellular location (Human Protein Atlas): Nuclear bodies; Focal adhesion sites
Pathways (Reactome):
Signal Transduction: Deactivation of the beta-catenin transactivating complex; Formation of the beta-catenin:TCF transactivating complex; NOTCH1 Intracellular Domain Regulates Transcription; Repression of WNT target genes
Gene Ontology:
Molecular function: protein binding; transcription corepressor activity
Biological process: negative regulation of canonical Wnt signaling pathway; negative regulation of DNA-templated transcription; animal organ morphogenesis; signal transduction; regulation of DNA-templated transcription
Cellular component: extracellular region; nuclear body; nucleoplasm; nucleus; transcription regulator complex
Genetic constraint (gnomAD): Loss-of-function variants: 74 observed, 88.07 expected, observed/expected ratio (o/e) 0.84, 90% interval 0.7 to 1.02. The synonymous counts are far from expectation, so gnomAD's model fits this gene poorly and the ratio says little. Missense variants: 1,037 observed, 965.76 expected, observed/expected ratio (o/e) 1.07, 90% interval 1.02 to 1.13. Synonymous variants: 498 observed, 407.52 expected, observed/expected ratio (o/e) 1.22, 90% interval 1.13 to 1.32.
Homologues: Orthologues: pig TLE2 (97% identical), dog TLE2 (96% identical), macaque TLE2 (93% identical), chimpanzee TLE2 (92% identical), mouse Tle2 (92% identical), rat Tle2 (91% identical), guinea pig TLE2 (76% identical), zebrafish tle2b (70% identical), tropical clawed frog tle2 (67% identical), zebrafish tle2a (67% identical), zebrafish tle2c (20% identical). Paralogues in human: TLE4 (70% identical), TLE1 (70% identical), TLE3 (69% identical), TLE6 (21% identical), TLE7 (21% identical), TLE5 (17% identical).
Diseases named in the same sentence as TLE2 in open-access papers:
TLE2 is named in the same sentence as 22 diseases in open-access papers, as found by Europe PMC text mining. Sharing a sentence is not in itself a finding about the gene and the disease. The quoted sentences say what the papers report.
bladder cancer (2 papers, 2019 to 2020). "SMARCAL, a chromatin remodeling factor, decreases telomere-replication stress related to carcinogenesis, and TLE2 is highly expressed in patients with early stage bladder cancer and correlates with favorable prognosis." (PMID 33221751, 2020). "In our study, expression of ANLN and TLE2 correlate with the therapeutic targets for bladder cancer as indicated in existing research and clinical trials." (PMID 31766561, 2019). "ANLN and TLE2 are promising biomarkers for individualized bladder cancer therapy including cancer subclassification and informed MIBC prognosis." (PMID 31766561, 2019).
ovarian carcinoma (2 papers, 2019 to 2021). A malignant neoplasm originating from the surface ovarian epithelium. "Inhibition of TLE2 expression in ovarian cancer increases the proportion of side population cells in tumors." (PMID 33747079, 2021). "Genomic deletion at TLE2 (19p13.3) was frequent in ovarian cancer (84%)." (PMID 31578411, 2019). "In summary, using a functional genomics screen, we identified six novel genes, MSL3, ZNF691, VPS45, ITGB3BP, TLE2, and ZNF498, that regulate the proportion of SP cells in ovarian cancer." (PMID 31578411, 2019). "In this study, we identified six novel genes, MSL3, ZNF691, VPS45, ITGB3BP, TLE2, and ZNF498 whose expression altered the proportion of the SP cells of ovarian cancer cells through a functional genomics screen." (PMID 31578411, 2019). "In conclusion, through a functional genomics screen using an shRNA library we identified six novel genes; MSL3, ZNF691, VPS45, ITGB3BP, TLE2 and ZNF498, whose downregulation individually increased the proportion of SP cells and the malignant phenotypes of ovarian cancer." (PMID 31578411, 2019).
pancreatic cancer (2 papers, 2022 to 2023). "TLE2 is linked to a good prognosis in pancreatic cancer, which regulates cell growth and gemcitabine sensitivity." (PMID 35077391, 2022). "TLE2 has been reported for many times to inhibit tumor progression and resistance to gemcitabine in pancreatic cancer, but the specific molecular mechanism is not clear." (PMID 38304253, 2023).
asthma (1 paper, 2015). "According to our data, Wnt pathway involves three common DCGs including FZD8, FOXN1 and TLE2, among which only FZD8 was reported to participate in the pathogenesis of Asthma, and display abnormal expression in Chronic kidney disease." (PMID 26450611, 2015). "There are no literatures on the roles of FOXN1 and TLE2 in Asthma, T2D and Chronic kidney disease in the public domain." (PMID 26450611, 2015).
astrocytoma (1 paper, 2017). "Recent studies also suggest that TLE2 is specifically expressed in grade I astrocytoma as compared to normal tissue and aggressive astrocytoma." (PMID 27852056, 2017).
breast carcinoma (1 paper, 2025). "In our study, we demonstrated reduced TLE2 expression in all breast cancer subtypes, which was likely unrelated to the activity of the identified miRNAs." (PMID 41463075, 2025).
endometrial cancer (1 paper, 2021). Primary or metastatic malignant neoplasm involving the endometrium (mucous membrane that lines the endometrial cavity). "Among them, CD3EAP and LY6H are prognostic risk genes for patients with endometrial cancer (HR > 1), while DMC1 and TLE2 are prognostic protective genes (HR < 1)." (PMID 33747079, 2021). "Our research also shows that TLE2 may play a tumor suppressor effect in endometrial cancer and that it is related to tumor cell stemness." (PMID 33747079, 2021).
esophageal squamous cell carcinoma (1 paper, 2021). Esophageal squamous cell carcinoma (ESCC) is a type of esophageal carcinoma (EC) that can affect any part of the esophagus, but is usually located in the upper or middle third. "Other studies have shown that TLE2 is downregulated by NDRG1 overexpression in esophageal squamous cell carcinoma, thereby promoting tumor occurrence and development by activating the Wnt signaling pathway." (PMID 33747079, 2021).
esophageal tumor (1 paper, 2019). "Previous research has shown that TLE2 was significantly suppressed and the level of β-catenin protein was increased in esophageal tumor cells, both of which were modulated by NDRG1 overexpression." (PMID 31766561, 2019).
Insulin resistance (1 paper, 2019). Increased resistance towards insulin, that is, diminished effectiveness of insulin in reducing blood glucose levels. "Rho family GTPase 3 (RND3), PARD6A, TLE2, FBLN2, COL4A1, and COL4A2 are novel biomarkers for the development of insulin resistance." (PMID 30678306, 2019).
meningioma (1 paper, 2019). A generally slow growing tumor attached to the dura mater. "Since then, TLE2 and TLE3 have also been shown to be induced during the malignant progression of meningiomas." (PMID 30719233, 2019).
prostate carcinoma (1 paper, 2013). A carcinoma that arises from epithelial cells of the prostate gland. "Moreover, the annotated genes in the constructed network, such as APC, AXIN1, AKT2, CCND2, CAV1, TLE2 and TCF4, are essential regulatory components of these pathways in prostate cancer." (PMID 23782521, 2013).
thymoma (1 paper, 2022). A neoplasm arising from the epithelial cells of the thymus. "In contrast, levels of nuclear inhibitors were variably higher in thymomas and TCs than in NTs: TLE2 and TCF4 were significantly (p <0.01) higher in B3 thymomas and TCs, TLE4 only in B3 thymomas and TCF3 only in AB thymomas." (PMID 35965500, 2022).
urothelial carcinoma (1 paper, 2019). A malignant neoplasm derived from the transitional epithelium of the urinary tract (urinary bladder, ureter, urethra, or renal pelvis). "ANLN showed overexpression in basal-like urothelial carcinoma cell lines and patients, while TLE2 showed significantly higher expression in luminal-like urothelial carcinoma cell lines and patients." (PMID 31766561, 2019).
tumor (6 papers, 2019 to 2023). "ANLN expression was confirmed to be up-regulated in the majority of tumor samples (26/31, 83.87%), while TLE2 was down-regulated in the majority of tumor samples (25/31, 80.64%)." (PMID 31766561, 2019). "CASKIN2, TLE2, USP20, SPRN, ARSG, MIR106B, and MIR98 were considered to be substantially expressed in the low-risk group, suggesting that these genes may be PAAD tumor suppressor genes." (PMID 35077391, 2022). "Many studies have shown that TLE2 has a tumor suppressor effect." (PMID 33747079, 2021). "In BLCA tumor samples, ANLN expression was up-regulated (median expression 16.72) compared to normal tissues (median expression 1.54), while TLE2 expression was down-regulated (median expression 22.27) compared to normal tissues (median expression 60.99)." (PMID 31766561, 2019).
cancer (4 papers, 2007 to 2025). A tumor composed of atypical neoplastic, often pleomorphic cells that invade other tissues. "Anilin actin binding protein (ANLN) and transducing-like enhancer protein 2 (TLE2) are associated with cancer patient survival and progression." (PMID 31766561, 2019). "High levels of TLE2 were associated with a better prognosis in bladder and pancreatic cancers." (PMID 41463075, 2025). "The level of APH1A, CTBP1, HEY1, HEY2, JAG2, NOTCH4 was significantly higher in cancer samples compared to the control group, while the concentration of DTX1 TLE2, TLE4 was below the detection threshold." (PMID 41463075, 2025). "In silico RNA-seq data from the Cancer Cell Line Encyclopedia showed ANLN and TLE2 expression levels in TPM (transcripts per million) for 25 BLCA cell lines, with different molecular subtypes of each (basal, luminal, and mixed)." (PMID 31766561, 2019). "Additional experiments are required to determine whether changes in the novel candidate cancer genes (FCGBP and TLE2) are indeed oncogenic." (PMID 18688287, 2007). "There are no published reports regarding a role for TLE2 in cancer." (PMID 31578411, 2019).
TLE2 also shares sentences with these, for which no sentence is quoted: Alzheimer disease (1 paper); cardiac sarcomas (1); chronic kidney disease (1); Obesity (1); primary immunodeficiency (1); sarcoma (1).